BTLA (B and T lymphocyte associated)
Diseases named in the same sentence as BTLA in open-access papers (continued):
Sharing a sentence is not in itself a finding about the gene and the disease.
lung cancer (continued). "Meanwhile, neither EBV strain can effectively induce LAG3 and BTLA expression in lung cancer cells, suggesting that these molecules were mainly expressed within the infiltrating immune cells in the tumor tissue." (PMID 31159203, 2019). "Similarly, the expression of BTLA was increased on CD4+ T cells and CD8+ T cells isolated from pleural effusion of lung cancer patients, indicating BTLA might mediate a negative cosignal for local immune response." (PMID 34163466, 2021).
chronic lymphocytic leukemia (14 papers, 2016 to 2025). "Another case–control study also found that BTLA rs1982809 polymorphism were associated with chronic lymphocytic leukemia." (PMID 31774112, 2019). "Rs1982809 is a functional single nucleotide polymorphism (SNP) that affects BTLA 3′-UTR activity and BTLA expression, and has been found to be associated with a higher incidence of renal cell carcinoma, chronic lymphocytic leukemia and esophagogastric junction adenocarcinoma." (PMID 33859648, 2021). "In addition, another study indicated that BTLA rs1982809 G and rs2705511 C alleles were more frequent in patients with chronic lymphocytic leukemia compared with healthy controls." (PMID 31774112, 2019). "Among B-cell non-Hodgkin lymphomas (NHL), only small lymphocytic lymphoma (B-SLL) exhibited a strong BTLA signal in all cases." (PMID 38233898, 2024). "Dysregulation of BTLA has been found in chronic lymphocytic leukemia, and the inhibition of BLTA in patients with chronic lymphocytic leukemia can effectively treat chronic lymphocytic leukemia." (PMID 37511932, 2023). "The aim of this study was to determine the association between polymorphisms in gene encoding B- and T-lymphocyte attenuator (BTLA) and susceptibility to chronic lymphocytic leukemia (CLL) and their influence on mRNA expression of BTLA gene in T and B cells from CLL patients (pts)." (PMID 27933341, 2016). "Instead, an anti-BTLA monoclonal antibody has been shown to deplete chronic lymphocytic leukemia (CLL) and boost natural killer (NK) cell-mediated responses ex vivo by increasing IFN-γ production and cytotoxic capability in antibody-dependent cytotoxicity (ADCC)." (PMID 38785930, 2024). "Additionally, the highest levels of BTLA among B-NHL were present on chronic lymphocytic leukemia (CLL) neoplastic B-cells." (PMID 38233898, 2024). "High expression of BTLA was also observed in B cell malignancies, in particular in chronic lymphocytic leukemia (CLL)." (PMID 27933341, 2016). "In B-cell lymphomas, such as chronic lymphocytic leukemia (CLL) and diffuse large B-cell lymphoma (DLBCL), as well as in T cell tumors, BTLA is frequently expressed on tumor-derived lymphocytes and is associated with a poor prognosis." (PMID 40574024, 2025). "Despite the fact that available agents targeting HVEM/BTLA have shown encouraging results in epithelial ovarian carcinoma and chronic lymphocytic leukemia, there is no published study to evaluate the therapeutic efficacy of HVEM/BTLA inhibition in NSCLC." (PMID 40985894, 2025).
gastric cancer (14 papers, 2019 to 2025). A primary or metastatic malignant neoplasm involving the stomach. "The high expression of BTLA in gastric cancer tissue is associated with poor prognosis such as lymph node metastasis and tumor invasion." (PMID 36552785, 2022). "BTLA expression in gastric cancer and lymphoma is also reported associate with poor prognosis." (PMID 31783776, 2019). "In gastric cancer, a significantly increased BTLA expression was seen compared to dysplastic and metaplastic gastric cancer precursor lesions in an mRNA analysis." (PMID 38928307, 2024). "On protein level analyzed by immunohistochemistry, BTLA expression in metaplastic and gastric cancer lesions was significantly increased compared to dysplastic lesions." (PMID 38928307, 2024). "What’s more, BTLA expression was found on tumor cells in lung adenocarcinoma patients as well as on tumor cells in gastric cancer." (PMID 36741370, 2022). "In gastric cancer, high expression of BTLA correlates with a poor prognosis on OS as well as with lymph node metastasis." (PMID 36741370, 2022). "Increased expression of B- and T-lymphocyte attenuator (BTLA) is detected on gastric cancer cells, which metastasize to the lymph nodes." (PMID 32902664, 2021). "Previous researches have shown the up-regulation of BTLA in gastric cancer, pancreatic cancer and lymphocytic leukemia and BTLA overexpression has been found to be associated with an immunosuppressive microenvironment." (PMID 34163466, 2021). "Reports indicating high BTLA expression were found in gastric cancer, pancreatic cancer, and chronic lymphocytic leukemia (CLL)/small lymphocytic leukemia." (PMID 34940257, 2021). "Both studies on lung and gastric cancers assessed the BTLA expression by IHC with polyclonal anti-BTLA antibodies." (PMID 34532285, 2021). "Overexpression of BTLA for example was correlated with lower overall survival in colorectal cancer, whereas high expression of HVEM was associated with poor prognosis in breast cancer, gastric cancer and metastatic melanoma." (PMID 38928307, 2024). "However, it has been shown that BTLA is expressed on ovarian cancer, gastric cancer, and non-small-cell lung cancer." (PMID 36552785, 2022). "BTLA activation suppresses cancer-specific CD8+ T-cell proliferation and differentiation, and its high expression in whole cancer tissue or infiltrating T cells is associated with poor outcomes in patients with epithelial ovarian, gallbladder, and gastric cancers." (PMID 34948416, 2021). "High VISTA expression was independently correlated with high BTLA, TIM-3, and TNFRS14 checkpoints and with a diagnosis of pancreatic, small intestine, and stomach cancer." (PMID 38503143, 2024). "High VISTA expression was independently correlated with high BTLA, TIM-3, and TNFRSF14, and with a diagnosis of pancreatic, small intestine, and stomach cancer." (PMID 38503143, 2024). "It has been shown that the increased BTLA and HVEM levels correlate with the development and poor prognosis of gastric cancer patients, and that high BTLA expression may predict prognosis in patients in NSCLC." (PMID 36552785, 2022). "CTLA-4 and PD-1 are expressed in human solid tumor-derived cells, and recent studies have shown that BTLA is expressed in a small subpopulation of cancer cells from clinical tumor specimens mainly identified by immunohistochemical including NSCLC, gastric cancer, and ovarian cancer cells." (PMID 36552785, 2022). "They observed no BTLA staining in normal mucosal tissues, while BTLA-positive gastric cancer (GC) cells were found in 75.6% of patients." (PMID 38233898, 2024).
ovarian carcinoma (14 papers, 2019 to 2025). A malignant neoplasm originating from the surface ovarian epithelium. "Although these data provide important information about the biomolecular characteristics of ovarian cancer, we would like to emphasize the relevance of our study in evaluating BTLA as a diagnostic and prognostic factor." (PMID 35204342, 2022). "There are little data on the use of BTLA as a diagnostic and prognostic biomarker in ovarian cancer, especially when it comes to measuring protein levels in peritoneal fluid." (PMID 35204342, 2022). "Zhang and colleagues suggested that miR-32 overexpression inhibits ovarian cancer cell proliferation, by targeting B and T lymphocyte attenuator (BTLA), an activator of phosphatidylinositol-3 kinases (PI3K) which mediates cell proliferation and survival." (PMID 37160545, 2023). "Similar synergistic effects were achieved by combination with chemotherapy in ovarian carcinoma, where BTLA expression was related to poor outcome." (PMID 37649037, 2023). "We observed significantly higher serum BTLA levels in patients with ovarian cancer (1418.8 pg/mL vs. 454.7 pg/mL in patients with benign ovarian lesions)." (PMID 35204342, 2022). "A recent in vivo study of ovarian carcinoma in mice concluded and demonstrated a survival benefit to using BTLA inhibition." (PMID 35159017, 2022). "The low expression levels of MiR-32 and its target on BTLA in ovarian cancer cells can help inspire treatment options for ovarian cancer." (PMID 35464451, 2022). "For this reason, we preclinically tested the chemotherapeutic agent paclitaxel in combination with an immune checkpoint inhibitor, anti-BTLA Ab, in an animal model of ovarian cancer." (PMID 31753019, 2019). "Additionally, the study beyond miR-155, demonstrated that miR-32, one of the downregulated miRNAs in ovarian cancer, exerts inhibitory effects on the proliferation, migration, and invasion of ovarian cancer cells by targeting BTLA." (PMID 38233898, 2024). "BTLA blockade together with the chemotherapeutic agent paclitaxel significantly reduced tumor size and improved survival compared to both monotherapies in murine models of ovarian carcinoma." (PMID 37649037, 2023). "BTLA, determined in peritoneal fluid, is an unfavorable prognostic factor for ovarian cancer." (PMID 35204342, 2022). "Interestingly, in ovarian carcinomas BTLA expression was mainly identified in B lymphocytes rather than T or NK cells, and the BTLA blockade antitumoral effect was caused by inhibiting a specific subset of B lymphocytes rather than stimulating T or NK cell function." (PMID 35164813, 2022). "Similarly, the importance of BTLA in the microenvironment of ovarian cancer has recently been reported and, though the immune regulatory pathway might be more complex, anti-BTLA therapy might also be beneficial in ACT." (PMID 32547707, 2020). "The median concentrations of the studied proteins (BTLA, CD27, CD28 and CD80) were statistically significantly higher in serum of patients in the ovarian cancer group (group A) compared to serum concentrations in patients with benign ovarian lesions (group B)." (PMID 35204342, 2022). "The expression of MiR-32 is markedly lower in ovarian cancer tissues than that in adjacent normal tissues; miR-32 also directly targets the 3′-UTR of BTLA." (PMID 35464451, 2022). "The cutoff values for BTLA, CD27, CD70, CD28 and CD80 that were elevated in the serum of patients with ovarian cancer were calculated using ROC curve analysis." (PMID 35204342, 2022). "A high expression of BTLA indicated a poor prognosis of OSCC, which is in accordance with the results of a previous study on ovarian cancer." (PMID 35127742, 2021). "A negative feedback loop was formed between miR-32 and BTLA, regulating the malignant behavior of ovarian cancer cells." (PMID 35464451, 2022).
ovarian carcinoma (continued). "BTLA, CD28 and CD80 may also contribute to the diagnosis of ovarian cancer, but their possible insufficient sensitivity and specificity as diagnostic markers should be taken into account." (PMID 35204342, 2022). "BTLA and CD27 are unfavorable prognostic factors for ovarian cancer." (PMID 35204342, 2022).
rheumatoid arthritis (14 papers, 2011 to 2024). A chronic, systemic autoimmune disorder characterized by inflammation in the synovial membranes and articular surfaces. "We, therefore, examined the possible association between BTLA and rheumatoid arthritis (RA), systemic lupus erythematosus (SLE), and Sjögren's syndrome (SS) by conducting a case-control genetic association study." (PMID 21403914, 2011). "B- and T-lymphocyte attenuator (BTLA) knock-out mice gradually develop multi-organ inflammatory infiltrates and a hepatitis-like disease, whilst a gene polymorphism in humans is associated with rheumatoid arthritis." (PMID 30349540, 2018). "Moreover, a single-nucleotide polymorphism (SNP) in the ITIM region of BTLA was reported to associate with increased susceptibility to rheumatoid arthritis." (PMID 23450201, 2013). "At the beginning in literature, there were only a few studies that addressed BTLA gene polymorphisms, and majority of them have investigated its role in susceptibility to autoimmune diseases, such as rheumatoid arthritis (RA), systemic lupus erythematosus (SLE) and type 1 diabetes mellitus." (PMID 33519815, 2020). "Another study also revealed an association between another BTLA SNP and rheumatoid arthritis, but not with systemic lupus erythematosus or Sjogren’s syndrome." (PMID 23450201, 2013). "The correct title is: The Expression of BTLA Was Increased and the Expression of HVEM and LIGHT Were Decreased in the T Cells of Patients with Rheumatoid Arthritis." (PMID 28253339, 2017). "In rheumatoid arthritis (RA) patients, BTLA-expressing CD3+/CD4+/CD8+ T cell proportions are remarkably increased, and the swollen joint count is negatively correlated with the percentage of BTLA+CD8+ T cells." (PMID 33859648, 2021).
systemic lupus erythematosus (14 papers, 2011 to 2025). An autoimmune multi-organ disease typically associated with vasculopathy and autoantibody production. "Consistent with an inhibitory role for BTLA, the disease is exacerbated in BTLA-deficient lupus mice." (PMID 34899718, 2021). "BTLA deficiency accelerates the lupus-like phenotype in autoimmune-prone MRL-lpr/lpr mice, and severe lymphocytic infiltration is detected in the lungs, kidneys, salivary glands, joints, and pancreas." (PMID 33859648, 2021). "Moreover, the enhancement of BTLA expression on aTregs is significantly associated to the presence of circulating anti-dsDNA autoAbs, which are characteristic for lupus (MFI 3499 ± 620 in the group of patients with anti-dsDNA autoAbs vs MFI 2064 ± 228 in HC, p<0.05)." (PMID 34899718, 2021). "Interestingly, in the MRL/lpr lupus mouse-model, characterized by TFH hyperactivity and Tregs dysfunction, BTLA deficiency leads to exacerbation of lupus symptoms and reduced survival, suggesting that the BTLA pathway plays important roles in controlling the disease development." (PMID 34899718, 2021). "In the MRL/lpr lupus mouse model, BTLA deletion exacerbates lupus, suggesting the protective role of BTLA in SLE pathogenesis." (PMID 41373483, 2025). "We observed a significant increase in the frequency of DN3 B cells with very low BTLA expression in lupus patients, particularly in those with anti-dsDNA antibodies." (PMID 39768154, 2024). "We very interestingly evidenced the existence of a DN memory B cell subset expressing very low levels of BTLA, which is enhanced in active lupus patients." (PMID 39768154, 2024). "We evidenced the existence of double-negative (DN; IgD−CD27−) memory B cells expressing very low levels of BTLA, which are enhanced in active lupus patients." (PMID 39768154, 2024). "More importantly, we identified a population of memory B cells with very low levels of surface BTLA in lupus patients." (PMID 39768154, 2024). "This enhancement of lupus symptoms is associated with a shortened survival rate, suggesting a protective role of the BTLA pathway in lupus pathogenesis." (PMID 39768154, 2024). "In the MRLlpr/lpr lupus mouse model, the genetic deletion of BTLA leads to the development of exaggerated lymphoproliferation, infiltration of inflammatory cells in organs, and an increase in autoantibody production." (PMID 39768154, 2024). "Collectively, these data show that DN3 B cells, which express low levels of BTLA and display characteristics of plasmablast precursors, are enriched in lupus patients as supported by both our study and previous findings." (PMID 39768154, 2024). "The BTLA signaling pathway is altered in SLE T cells, and the impaired capacity of BTLA can be corrected by normalizing the lipid metabolism in lupus CD4+ T cells." (PMID 35371016, 2022). "In the present work, we aimed at delineating the expression pattern of BTLA on CD4+ T cell subsets suspected to play a key role in lupus pathogenesis, such as circulating follicular helper T cells (cTFH) and regulatory T cells (Tregs)." (PMID 34899718, 2021). "To investigate the clinical significance of higher BTLA expression on lupus Tregs, we then analyzed BTLA levels (MFI) in relation to disease activity assessed by the SLEDAI score." (PMID 34899718, 2021). "An extensive knowledge of BTLA expression on all immune cell subsets involved in lupus pathogenesis is absolutely required to envisage targeting this molecule in the context of new therapeutic strategies." (PMID 34899718, 2021). "Very interestingly, we observed that the expression level of BTLA on aTregs inversely correlated with their frequency in PBMCs from lupus patients (p<0.01)." (PMID 34899718, 2021). "Our phenotypic analysis revealed a higher ex vivo BTLA expression on aTregs from lupus patients than HC." (PMID 34899718, 2021).